HDAC9 (histone deacetylase 9)
Diseases named in the same sentence as HDAC9 in open-access papers (continued):
Sharing a sentence is not in itself a finding about the gene and the disease.
aneurysm (8 papers, 2016 to 2025). Bulging or ballooning in an area of an artery secondary to arterial wall weakening. "This suggests that HDAC9 expression is not only an indicator of aneurysm formation but also related to brain injury in the rupture of IA." (PMID 37573538, 2024). "Targeting HDAC9-BRG1-MALAT1 complex by deletion of Malat1 or Hdac9 in vivo restores contractile protein gene expression, improves aortic mural architecture, and inhibits experimental aneurysm growth in Fbn1C1039G/+ (Marfan syndrome) mouse model." (PMID 32241300, 2020). "Disruption of Malat1 or Hdac9 restores contractile protein expression, improves aortic mural architecture, and inhibits experimental aneurysm growth." (PMID 29520069, 2018). "Immunohistochemistry from TAA samples also showed upregulation of HDAC9 in aneurysm tissue from syndromic, sporadic, and familial cases of TAA." (PMID 29520069, 2018). "In SMCs of aortas from an aneurysm mouse model, increased expression and colocalization of HDAC9, BRG1, and MALAT1 was found and deletion of MALAT1 or HDAC9 restored the contractile protein expression and inhibited aneurysm growth." (PMID 30893946, 2019).
fibrosis (8 papers, 2013 to 2023). the formation of excess fibrous connective tissue in an organ or tissue in a reparative or reactive process. "Compared with control group, AA-treated mice exhibited obvious deposition of extracellular matrix (ECM), but tubule-specific deletion of HDAC9 alleviated kidney tubulointerstitial fibrosis evidenced by Masson ́s trichrome and Sirius Red staining." (PMID 37230975, 2023).
Hepatic steatosis (8 papers, 2014 to 2025). Steatosis is a term used to denote lipid accumulation within hepatocytes. "FOXF2 has been shown to downregulate the expression of Insulin Receptor Substrate 1 (IRS1) in adipose tissue, thereby reducing glucose uptake, and HDAC9 has been implicated in adipocyte hypertrophy, IR, and hepatic steatosis." (PMID 40699860, 2025).
large artery stroke (7 papers, 2012 to 2022). Stroke caused by the blockage of blood flow in one of the large arteries feeding the brain. "The risk allele (A) in HDAC9 gene has a frequency of 20% across all ethnicities with 42% increased risk of large artery stroke for 1 copy and a 102% increase in risk for both copies of the risk allele." (PMID 35433850, 2022). "A previous genome-wide association study showed that a single nucleotide polymorphism (SNP) rs2107595 in histone deacetylase 9 (HDAC9) gene was associated with large artery stroke (LAS) in Caucasians." (PMID 27494404, 2016). "A variant in the histone deacetylase 9 (HDAC9) gene is associated with large artery stroke." (PMID 29247141, 2018). "Additionally, our findings highlight the potential of HDAC9 inhibition as a therapeutic intervention to potentially prevent progression of large artery stroke, and provide a cellular human hiPSC-derived disease model with easy phenotypic readout for high-throughput screening of such inhibitors." (PMID 35433850, 2022). "The mechanism by which variants in HDAC9 increase large artery stroke risk is not immediately clear, although the specific association with large artery stroke might suggest that they act through increasing atherogenesis." (PMID 23016624, 2012).
osteoarthritis (7 papers, 2010 to 2023). A noninflammatory degenerative joint disease occurring chiefly in older persons, characterized by degeneration of the articular cartilage, hypertrophy of bone at the margins and changes in the synovial membrane. "The HDAC9-PIASy-RNF4 axis promotes chondrocyte hypertrophy by regulating the sumo and ubiquitination of Nkx3.2/Bapx1, which is degraded by the proteasome, according to studies on HDAC9 in osteoarthritis." (PMID 35873487, 2022).
osteoporosis (7 papers, 2020 to 2026). A condition of reduced bone mass, with decreased cortical thickness and a decrease in the number and size of the trabeculae of cancellous bone (but normal chemical composition), resulting in increased fracture incidence. "Our results indicated that the inhibition of HDAC9 could alleviate aged-related bone mass loss in mice, which suggests its potential as a target in the clinical treatment of senile osteoporosis." (PMID 32620134, 2020). "To determine whether HDAC9 functions in vivo, we used a lentivirus containing HDAC9 shRNA to inhibit HDAC9 expression in the bone marrow of aged mice with senile osteoporosis." (PMID 32620134, 2020).
astrocytomas (6 papers, 2008 to 2025). "The protein levels of class II HDAC9 were also lower in high-grade astrocytomas than in low-grade astrocytomas and normal brain." (PMID 24202337, 2013). "The protein levels of class II HDAC9 were also lower in high-grade astrocytomas than in low-grade astrocytomas and normal brain tissue." (PMID 18713462, 2008). "Protein levels of class II HDAC9 are also lower in high-grade astrocytomas." (PMID 40940748, 2025). "Furthermore, contrasting to normal tissue and low grade astrocytoma, HDAC9 was significantly upregulated in GBM patients according to French's data, p < 0.05." (PMID 25760078, 2015).
cardioembolic stroke (6 papers, 2012 to 2023). "We verified previous associations for cardioembolic stroke near PITX2 (p=2·8×10−16) and ZFHX3 (p=2·28×10−8), and for large-vessel stroke at a 9p21 locus (p=3·32×10−5) and HDAC9 (p=2·03×10−12)." (PMID 23041239, 2012). "The discovery meta-analysis confirmed associations at genome-wide significance levels for HDAC9 with large-vessel disease, and for both PITX2 and ZFHX3 with cardioembolic stroke." (PMID 23041239, 2012). "The population attributable risks in the METASTROKE discovery cohort were estimated as 5·8% for PITX2 and 7·0% for ZFHX3 in cardioembolic stroke, and 4·5% for HDAC9 and 7·2% for 9p21 in large-vessel disease." (PMID 23041239, 2012).
esophageal squamous cell carcinoma (6 papers, 2014 to 2023). Esophageal squamous cell carcinoma (ESCC) is a type of esophageal carcinoma (EC) that can affect any part of the esophagus, but is usually located in the upper or middle third. "In esophageal squamous cell carcinoma the miR-30d-5p can modulate HDAC9 expression and the long non-coding (lncRNA) LOC440173 acts as a sponge to sustain HDAC9 levels and the tumorigenic process." (PMID 33513699, 2021).
kidney (6 papers, 2008 to 2025). "Collectively, our studies demonstrate that HDAC9 contributes to G2/M arrest in tubular epithelial cells by regulating the activation of STAT1, followed by promoting production of profibrotic cytokine, finally causing kidney tubulointerstitial fibrosis." (PMID 37230975, 2023).
carotid atherosclerosis (5 papers, 2015 to 2022). A thickening and loss of elasticity of the walls of carotid arteries that occur with formation of atherosclerotic plaques. "In the present study we investigated the association between the rs2107595 of the HDAC9 gene and advanced carotid atherosclerosis in a Slovenian cohort of subjects." (PMID 32284067, 2020). "Moreover, several studies have found an association between the rs2107595 polymorphism of the HDAC9 gene and the onset and progression of carotid atherosclerosis, ischemic and hemorrhagic stroke, large vessel atherosclerotic stroke (LVAS), and atherosclerotic coronary artery disease." (PMID 32284067, 2020).
Clear Cell Renal Cell Carcinoma (5 papers, 2020 to 2025). "Our previous study suggested that low HDAC9 expression might facilitate clear cell renal cell carcinoma (ccRCC) cell growth, and we further found that HDAC9 was closely related to immunity and increased the infiltration levels of a variety of immune cells." (PMID 35239708, 2022).
rhabdoid tumor (5 papers, 2013 to 2024). An aggressive malignant embryonal neoplasm usually occurring during childhood. "In particular, in malignant rhabdoid tumor cell lines, increased binding of epigenetic silencers HDAC9 and MEF2D at SMARCA2 promoter sites has been associated with such heterozygous polymorphisms." (PMID 32575483, 2020). "Specifically, we observed that HDAC9 expression in 3 BRM-deficient Rhabdoid tumors was 80±25-fold higher as compared to the BRM-positive Rhabdoid tumors." (PMID 24913006, 2014). "In primary BRM-deficient Rhabdoid tumors, HDAC9 was also found to be highly overexpressed." (PMID 24913006, 2014). "Based on our experimental data, targeting HDAC9 might be an avenue of therapy for Rhabdoid tumors, since BRM re-expression seems to be important to block the growth of this tumor." (PMID 24913006, 2014). "As the knockdown of HDAC9 induces BRM in both non-Rhabdoid as well as in Rhabdoid cancer cell lines, these data support the hypothesis that HDAC9 is central to the epigenetic suppression of BRM in human tumors." (PMID 24913006, 2014).
urothelial bladder cancer (5 papers, 2014 to 2024). "HDACs have also been studied in non-urothelial bladder cancer, with one study finding HDAC4, HDAC7, and HDAC9 to be overexpressed in basal-squamous bladder cancer." (PMID 36980741, 2023).
aortic aneurysm (4 papers, 2016 to 2018). A ruptured aneurysm located in the wall of the proximal portion of the descending aorta proceeding from the arch of the aorta. "MALAT1 is necessary for targeting HDAC9 to the nucleus and depletion of MALAT1 or HDAC9 reverses deleterious cellular phenotypes and modifies VSMC-dependent pathology including inhibiting experimental aortic aneurysm." (PMID 29520069, 2018).
Burkitt lymphoma (4 papers, 2014 to 2024). A rare form of malignant mature B-cell non-Hodgkin lymphoma. "Monoallelic knockout of HDAC9 in the Raji Burkitt's lymphoma cell line (biallelic forms were non-viable; data not shown) led to reductions in HDAC9, consistent with a decrease in gene dosage." (PMID 27799148, 2016).
embryonal carcinoma (4 papers, 2009 to 2022). A non-seminomatous malignant germ cell tumor characterized by the presence of large germ cells with abundant cytoplasm resembling epithelial cells, geographic necrosis, high mitotic activity, and pseudoglandular and pseudopapillary structures formation. "We further identified two pivot AS-related molecules (SOX2 and HDAC9) involved in AS regulation, which were validated in embryonal carcinoma and seminoma cell lines." (PMID 36713456, 2022). "Moreover, data from TCGA showed that SOX2 was significantly overexpressed in embryonal carcinoma cells, while HDAC9 expression was increased in seminoma cells." (PMID 36713456, 2022).
endothelial dysfunction (4 papers, 2016 to 2025). In vascular diseases, endothelial dysfunction is a systemic pathological state of the endothelium (the inner lining of blood vessels) and can be broadly defined as an imbalance between vasodilating and vasoconstricting substances produced by (or acting on) the endothelium. "We further found that HDAC9 suppressed autophagy, which was associated with endothelial dysfunction." (PMID 26865248, 2016). "Most importantly, HDAC9 has been shown to be critical for ox-LDL-induced endothelial dysfunction." (PMID 34872444, 2021).
ependymoma (4 papers, 2015 to 2023). A WHO grade II, slow growing tumor of children and young adults, usually located intraventricularly. "However, our combined approach identified novel potential biomarker candidates in ependymoma with a known relationship to cancer: ERRB2, EGFR, TWIST1, CDK4, HDAC9, and ARHGEF5 genes." (PMID 26185765, 2015).
glomerulosclerosis (4 papers, 2021 to 2024). A hardening of the kidney glomerulus caused by scarring of the blood vessels. "Additional studies also revealed that the silencing of histone deacetylase 9 (HDAC9) mitigated glomerulosclerosis, inflammatory cytokine release, podocyte apoptosis, and renal injury, all of which were achieved through the JAK2/STAT3 pathway." (PMID 38671903, 2024). "Silencing of HDAC9 attenuates glomerulosclerosis, inflammatory cytokine release, podocyte apoptosis and injury in db/db mice." (PMID 35910382, 2022).
papillary thyroid cancer (4 papers, 2015 to 2023). "Our previous genome-wide association study found two important genes being related to extracranial CAS, papillary thyroid carcinoma susceptibility candidate 3 (PTCSC3) and HDAC9." (PMID 36230983, 2022).
serous ovarian cancer (4 papers, 2016 to 2023). "In contrast, high expression levels of HDAC9 were associated with a higher survival rate for patients with non-serous ovarian cancer." (PMID 37894746, 2023). "In contrast, high expression levels of HDAC9 were associated with high survival rates for patients with non-serous ovarian cancer (p = 0.041)." (PMID 35203583, 2022). "Our results showed that high expression levels of HDAC9 were associated with a poor prognosis for patients with serous ovarian cancer (p = 0.037)." (PMID 35203583, 2022). "In serous ovarian cancer cells, overexpressed HDAC9 can activate EMT and promote cell migration and invasion via increasing the nuclear localization of forkhead box O1 (FOXO1) and promoting the expression of the transforming growth factor β (TGFβ)." (PMID 37894746, 2023). "In non-serous ovarian cancer cells, HDAC9 decreases the acetylation of β-catenin K49 and induces β-catenin translocation to the cytoplasm, inactivating EMT and inhibiting cell migration and invasion." (PMID 37894746, 2023). "HDAC9 expression levels were negatively correlated with the prognosis of patients with high-grade serous ovarian cancer." (PMID 37894746, 2023). "In this study, we found that patients with serous ovarian cancer with high expression of HDAC9 had poor prognoses." (PMID 35203583, 2022). "On the contrary, patients with non-serous ovarian cancer with high expression of HDAC9 had higher survival rates." (PMID 35203583, 2022). "In serous ovarian cancer, overexpressed HDAC9 can increase the nuclear localization of FOXO1 and promote the expression of TGF-β." (PMID 35203583, 2022). "In non-serous ovarian cancer, downregulated HDAC9 may activate the EMT program by activating β-catenin signaling." (PMID 35203583, 2022). "Our data suggest that FOXO1 inhibitors and TGF-β inhibitors may enhance the therapeutic effect of HDAC9 inhibitors on serous ovarian cancer." (PMID 35203583, 2022). "Taken together, these results suggest that HDAC9 may play different roles in serous and non-serous ovarian cancer." (PMID 35203583, 2022). "Our findings suggested that, in serous ovarian cancer, overexpressed HDAC9 may activate epithelial–mesenchymal transition (EMT) by increasing the nuclear accumulation of FOXO1." (PMID 35203583, 2022). "In non-serous ovarian cancer, an HDAC9 inhibitor combined with a β-catenin inhibitor may achieve a better therapeutic effect." (PMID 35203583, 2022). "In serous ovarian cancer, HDAC9 may promote cell migration by increasing the nuclear accumulation of FOXO1 and promoting TGF-β expression." (PMID 35203583, 2022). "In serous ovarian cancer, overexpressed HDAC9 may promote cell migration through the forkhead box protein O1 (FOXO1)/transforming growth factor-beta (TGF-β) axis." (PMID 35203583, 2022). "In serous ovarian cancer, overexpressed HDAC9 may activate epithelial–mesenchymal transition (EMT) by increasing nuclear accumulation of FOXO1." (PMID 36505774, 2022). "Serous ovarian cancer patients with high HDAC9 expression have a poor prognosis, while non-serous ovarian cancer patients with high HDAC9 expression have a higher survival rate." (PMID 36505774, 2022). "On the contrary, overexpressed HDAC9 may inhibit EMT by decreasing the nuclear accumulation of β-catenin and the acetylation of β-catenin at Lys-49 in non-serous ovarian cancer." (PMID 35203583, 2022). "We found that HDAC9 has tumor-promoting roles in serous ovarian cancer cells, whereas patients with non-serous ovarian cancer with high HDAC9 expression have higher survival rates." (PMID 35203583, 2022).
thoracic aortic aneurysm (4 papers, 2018 to 2025). An aneurysm formed in the wall of the proximal portion of the descending aorta proceeding from the arch of the aorta. "Increased HDAC9 expression is seen in human thoracic aortic aneurysm tissue and also in cell culture models of genetically perturbed vascular smooth muscle cells where increased HDAC9 is associated with increased MMP production and dysregulation of cytoskeletal genes." (PMID 34338228, 2021).
allergic asthma (3 papers, 2020 to 2025). A asthma with a basis in a pathological type I hypersensitivity reaction. "C2 may increase the acetylation of the Foxp3 promoter through the inhibition of HDAC9, thus inhibiting the occurrence of allergic asthma." (PMID 37215145, 2023).
aristolochic acid nephropathy (3 papers, 2015 to 2024). "Here, we find that Hdac9 expression is significantly induced in the mouse fibrotic kidneys, especially in proximal tubules, induced by aristolochic acid nephropathy (AAN) or unilateral ureter obstruction (UUO)." (PMID 37230975, 2023).
Brain atrophy (3 papers, 2018 to 2021). Partial or complete wasting (loss) of brain tissue that was once present. "Collectively, findings from our and other studies indicate that MEF2C and HDAC9 may participate in a pathway leading to NFT formation and brain atrophy." (PMID 29458411, 2018).
cerebral infarction (3 papers, 2020 to 2023). An ischemic condition of the brain, producing a persistent focal neurological deficit in the area of distribution of the cerebral arteries. "In this study, we observed the expression of HDAC9 after cerebral infarction, thus exploring its relationship with the occurrence of cerebral infarction, to further understand the mechanisms of HDACs in ischemic stroke." (PMID 33584204, 2020). "Meanwhile, TTC staining data indicated that HDAC9 overexpression could memorably attenuate the reduction of the cerebral infarction area, which was mediated by miR-101-3p agomiR in tMCAO young mice." (PMID 37250142, 2023). "Moreover, we proved that overexpression of miR-101-3p could improve cerebral infarction, neuronal morphology, and neuronal apoptosis in tMCAO young mice by lowering the expression of HDAC9." (PMID 37250142, 2023).
hyperlipidemia (3 papers, 2016 to 2022). "Therefore, by increasing HDAC9 expression, the minor allele of SNP rs2107595 may inhibit cholesterol efflux, then interact with hyperlipidemia to aggravate coronary atherosclerosis." (PMID 27494404, 2016). "In conclusion, by regulating HDAC9 expression and interacting with T2DM, hyperlipidemia and BMI status, the minor allele A of SNP rs2107595 increased CAD risk and the severity of coronary atherosclerosis." (PMID 27494404, 2016).